TBKBP1 (TBK1 binding protein 1)
Description:
Adapter protein which constitutively binds TBK1 and IKBKE playing a role in antiviral innate immunity.
Synonyms: KIAA0775; SINTBAD; ProSAPiP2
Tractability: PROTAC: ubiquitination databases record sites on it; a small molecule that binds it is known.
Gene: Protein-coding gene on chromosome 17 (47,694,030 to 47,712,063, forward strand). Ensembl gene ENSG00000198933.
Subcellular location (Human Protein Atlas): Nucleoplasm
Gene Ontology:
Molecular function: protein binding
Biological process: defense response to virus; type I interferon-mediated signaling pathway
Cellular component: cytoplasm; serine/threonine protein kinase complex
Genetic constraint (gnomAD): Loss-of-function variants: 44 observed, 51.11 expected, observed/expected ratio (o/e) 0.86, 90% interval 0.68 to 1.11. The synonymous counts are far from expectation, so gnomAD's model fits this gene poorly and the ratio says little. Missense variants: 774 observed, 673.87 expected, observed/expected ratio (o/e) 1.15, 90% interval 1.08 to 1.22. Synonymous variants: 385 observed, 309.83 expected, observed/expected ratio (o/e) 1.24, 90% interval 1.14 to 1.35.
Homologues: Orthologues: chimpanzee TBKBP1 (99% identical), dog TBKBP1 (95% identical), rat Tbkbp1 (93% identical), mouse Tbkbp1 (93% identical), rabbit TBKBP1 (92% identical), guinea pig TBKBP1 (69% identical), macaque TBKBP1 (67% identical), tropical clawed frog tbkbp1 (54% identical), zebrafish tbkbp1 (47% identical). Paralogues in human: AZI2 (18% identical).
Diseases named in the same sentence as TBKBP1 in open-access papers:
TBKBP1 is named in the same sentence as 10 diseases in open-access papers, as found by Europe PMC text mining. Sharing a sentence is not in itself a finding about the gene and the disease. The quoted sentences say what the papers report.
ankylosing spondylitis (2 papers, 2013 to 2022). An autoimmune chronic inflammatory disorder characterized by inflammation in the vertebral joints of the spine and sacroiliac joints. "Our purpose is to examine the influence of PPARGC1B, RUNX3 and TBKBP1 polymorphisms on the susceptibility to and the severity of ankylosing spondylitis in Chinese ethnic majority Han population." (PMID 23637848, 2013).
lung carcinoma (1 paper, 2021). "It is important to note, however, that stimulation of human A549 lung cancer cells and primary mouse lung cancer cells with several different growth factors (e.g., EGF; FBS; insulin) increased TBK1 S172 phosphorylation, which required TBKBP1 (TBK1 binding protein 1), a TBK1 adaptor protein." (PMID 34245780, 2021).
melanoma (1 paper, 2018). A malignant, usually aggressive tumor composed of atypical, neoplastic melanocytes. "To assess the in vivo role of Tbkbp1 in regulating CD8+ T cell responses, we employed a tumor immunity model involving inoculation of B16 murine melanoma cells expressing a surrogate antigen, chicken ovalbumin (OVA), to Tbkbp1-KO and WT mice." (PMID 30022064, 2018).
tumor (4 papers, 2018 to 2025). "Compared to WT mice, the Tbkbp1-KO mice had reduced tumor growth rate and improved survival rate, coupled with increased frequencies of IFNγ-producing CD8+ effector T cells in the tumor and draining lymph node." (PMID 30022064, 2018). "In support of this idea, deletion of IL-4 in Tbkbp1-KO mice, which blocked hyper-production of memory-like CD8+ T cells, abrogated their ability to mediate stronger tumor rejection and CD8+ effector T cell responses." (PMID 30022064, 2018).
cancer (2 papers, 2022 to 2024). A tumor composed of atypical neoplastic, often pleomorphic cells that invade other tissues. "Here we reviewed the activation of TBK1 in cancer cells induced by multiple signaling components, such as RalB/Sec5/TBK1 complex, TBK1/TBKBP1/CARD10/PKC complex and TNFR1-SC complex." (PMID 39279883, 2024).
TBKBP1 also shares sentences with these, for which no sentence is quoted: infection (4 papers); frontotemporal dementia (1); multiple sclerosis (1); ovarian carcinoma (1); prostate carcinoma (1).